IRAK4 (interleukin 1 receptor associated kinase 4)
Diseases named in the same sentence as IRAK4 in open-access papers (continued):
Sharing a sentence is not in itself a finding about the gene and the disease.
viral infections (14 papers, 2012 to 2025). "In particular, it has been shown that IRAK-4 deficient patients can control viral infection through both TLR3 or TLR independent production of type I IFN." (PMID 32038653, 2020). "Similar mechanisms likely contribute to protect MyD88- or IRAK4-deficient patients from viral infections." (PMID 25954804, 2015). "On the other hand, while patients genetically deficient for MYD88 or IRAK4 show enhanced susceptibility to mycobacteria, they are resistant to most viral infections." (PMID 25954804, 2015). "More recent data also show that patients with inherited MyD88 or IRAK-4 deficiency are at increased risk of severe hypoxemic COVID-19 pneumonia, underlining the need for close monitoring and aggressive supportive care during viral infections." (PMID 41369391, 2025). "Together with the reports of HHV6 disease in such patients, and the occurrence of severe influenza pneumonia in two patients from our cohort, these data suggest that MyD88- and IRAK-4–deficient patients may be prone to other severe viral infections, perhaps with low penetrance." (PMID 36880831, 2023). "Therefore, SLE patients treated with IRAK1 or IRAK4 inhibitors may have less risk for developing severe viral infection compared with patients given anti-IFN therapy." (PMID 27807192, 2016). "First, human pediatric patients with deficiency in TLR/IL-1R signaling molecules, MyD88 or IRAK-4, are predisposed to pyogenic bacterial infections, including S. pneumoniae, S. aureus, and P. aeruginosa, whereas other types of bacterial, fungal and viral infections are exceedingly rare." (PMID 23209417, 2012). "Further accumulation of cases and characterization of the molecular pathogenesis of IRAK4 deficiency are expected to elucidate the risk of viral infections and/or anti-NMDAR encephalitis in patients with IRAK4 deficiency." (PMID 33083971, 2021). "TLR7, MyD88, TRAF6, IRAK4 and NF-κB p65 mRNA were up-regulated after virus infection (p < 0.01) while down-regulated after oseltamivir and FTA treatment (p < 0.01)." (PMID 27128889, 2016). "Additionally, there were 3 cases of severe viral infection predisposition, 3 cases of bacterial infection predisposition, 1 case of HSE, and 1 case of IRAK4 deficiency." (PMID 41209815, 2025). "To date, no cases with anti-NMDAR encephalitis or severe virus infections have been reported in IRAK4-deficient patients." (PMID 33083971, 2021). "The results showed that the expression levels of TLR7, MYD88, IRAK4 and NF-κB were remarkably up-regulated upon viral infection, and Guizhi-and-Mahuang decoction and Yinqiao powder could down-regulate their expressions in wild type mice." (PMID 30151032, 2018). "IRAK4-deficient children are susceptible to infection by pyogenic bacteria until they reach puberty, but they are not more susceptible to viral infection." (PMID 27807192, 2016). "In contrast to MyD88 or IRAK-4 deficiencies, which cause severe, multi-organ disease, TIRAP deficiency may present with a milder phenotype and partially preserved immune responses, especially against viral infections." (PMID 41369391, 2025). "However, patients with MyD-88 and IRAK-4 deficiency show no impaired defense against viral infections, due to their normal functional natural killer cells as well as their retained ability to signal through TLR-3/-7/-9 and other non-TLR viral receptors." (PMID 25528552, 2014). "Virus infection induced significant increase in the mRNA levels of TLR7, MyD88, IRAK4 and NF-κB in wild type mice compared to blank control (P < 0.001)." (PMID 30151032, 2018). "We further demonstrated that virus infection increased protein expression levels of TLR7, MyD88, IRAK4 and NF-κB with western blotting, while Oseltamivir, Guizhi-and-Mahuang decoction, Yinqiao powder decreased their expression." (PMID 30151032, 2018).
viral infections (continued). "The levels of p-IRAK4, p-TAK1, and p-TBK1 were activated by SeV, but repressed by Sox4, indicating that Sox4 attenuates both TLR/MyD88/IRAK4/TAK1 and TLR/TRIF/TRAF3/TBK1 pathways in response to viral infections." (PMID 33517839, 2021). "The expression of IRAK4 was low upon viral infection, indicating that the TLR7 knockout might affect IRAK4 expression in the downstream pathway." (PMID 30151032, 2018). "Patients with mutations in downstream components of TLR signaling such as interleukin-1 receptor-associated kinase 4 (IRAK-4) and MyD88 are not susceptible to viral infections such as VZV, highlighting the functional redundancy in the TLR pathogen sensing pathway." (PMID 32038653, 2020).
Immunodeficiency (11 papers, 2008 to 2026). Failure of the immune system to protect the body adequately from infection, due to the absence or insufficiency of some component process or substance. "Strikingly, exome sequencing also revealed variants in immunodeficiency-associated genes (IRAK4, USB1), autoinflammatory disorders (PSTPIP1) and unexpected candidates like ETV6, and MAN1B1 revealing previously unrecognised pathways in SLE development." (PMID 41930824, 2026). "Bi-allelic recessive mutations in IRAK4 in humans described to date are loss-of-function and result in a clinical phenotype of immunodeficiency with variable susceptibility to infection with pyogenic bacteria." (PMID 37744344, 2023). "Interleukin-1 receptor-associated kinase 4 (IRAK4) deficiency (OMIM #607676) is a rare primary immunodeficiency of innate immune defect." (PMID 26825884, 2016). "The observation that the immunodeficiency of IRAK4- and MYD88-deficient children usually improves with age suggests a gradual compensation of the adaptive immune response with time or that the innate immune response is able to mature with age." (PMID 25886387, 2015). "The possibility of immunodeficiency was therefore considered and the children were subsequently demonstrated to be homozygous for an interleukin-1 receptor-associated kinase 4 (IRAK 4) deficiency." (PMID 24625087, 2014). "In contrast, children with an IRAK4-deficiency have a remarkably mild immunodeficiency with enhanced susceptibility to infection by only a narrow range of Gram positive bacteria, particularly S. aureus and S. pneumoniae." (PMID 20105294, 2010). "We previously reported an IRAK4-deficiency in a 4-year old child due to a homozygous single base substitution (C887T) in exon 8 of the IRAK4 gene that introduced a premature stop codon (Q293X); an identical mutation occurs in the majority of cases of IRAK4 immunodeficiency." (PMID 20105294, 2010). "Clinical features resulting from LYST mutations in CHS have much in common with immunodeficiencies caused by TLR signaling defects, such as conditions caused by autosomal recessive mutations in TLR adapters, IRAK-4 and MyD88 (OMIM# 610799, 607676, 612260)." (PMID 25528552, 2014). "Defects of IRAK-4 can lead to immunodeficiency with decreased cytokine production leading to increased susceptibility to infection with pyogenic bacteria, like staphylococci and streptococci during childhood." (PMID 19025640, 2008). "In particular, we suggest that screening for neuroinflammation with brain MRI should be undertaken in all patients with bi-allelic mutations in IRAK4 and also hypothesize than autoinflammation may be more prevalent that hitherto recognized in patients with typical IRAK-4 immunodeficiency." (PMID 37744344, 2023). "We therefore highlight that bi-allelic mutation in IRAK4 may be associated with a severe and complex autoinflammatory and neuroinflammatory phenotype that we have called NASA (neuroinflammation, autoinflammation, splenomegaly and anemia), in addition to immunodeficiency in humans." (PMID 37744344, 2023). "This emphasizes that there is functional impairment of the IRAK-4 pathway in patients with NASA, but that autoinflammation rather than immune deficiency predominates the clinical picture." (PMID 37744344, 2023). "IRAK4 and MYD88 deficiencies on the other hand appear to result in a narrow-spectrum immunodeficiency characterised by IPD and the absence of AED." (PMID 25886387, 2015).
melanoma (8 papers, 2014 to 2025). A malignant, usually aggressive tumor composed of atypical, neoplastic melanocytes. "Immunohistochemical studies on melanoma have shown that phosphorylated IRAK-4 is widely expressed in diseased tissues." (PMID 40165954, 2025). "In the melanoma cell lines, both IRAK4 and IRAK1 are highly expressed and activated, and promote primary melanoma progression." (PMID 27619757, 2016). "Inhibition of IRAK-1 and IRAK-4, using pharmacological inhibitor or siRNA, sensitized melanoma tumors expressing phosphorylated forms of these IRAKs to cytotoxic chemotherapies in vivo, raising the possibility that IRAK family proteins may be potential therapeutic targets in cancer." (PMID 25452754, 2014). "Given IRAK-4’s role in promoting cancer cell survival, we investigated IRAK-M’s part in melanoma survival following expression of IRAK-M by nucleofection, which achieved high protein expression levels in both melanomas and melanocytes." (PMID 32533049, 2020). "A combined treatment of vinblastine and small interfering RNAs (siRNAs) inhibited IRAK4 and IRAK1, showing reduced tumor growth and increased survival rate of melanoma xenograft model of mice." (PMID 27845762, 2016). "As previously discussed (in the Section IRAK-1) some melanomas constitutively express active, phosphorylated forms of IRAK-1 and IRAK-4." (PMID 25452754, 2014). "Constitutive phosphorylated states of IRAK4 and IRAK1 have been reported in melanoma patients." (PMID 27845762, 2016). "Our group has also found IRAK-1 and/or IRAK-4 to localize to the nucleus of melanoma cells, but not melanocytes (Geng, unpublished data)." (PMID 25452754, 2014). "Inhibiting IRAK-4 rather than IRAK-1 using shRNA was more effective at sensitizing melanoma tumors and T-ALL cells to chemotherapies." (PMID 25452754, 2014). "Patient-derived melanoma tumor samples also exhibited increased expression of phosphorylated IRAK-4 although there did not appear to be a correlation between p-IRAK levels and melanoma stage." (PMID 25452754, 2014).
Sepsis (8 papers, 2012 to 2026). Sepsis is defined as life-threatening organ dysfunction caused by a dysregulated host response to infection. "Fourteen tag single nucleotide polymorphisms (tagSNPs) in MyD88, IRAK1, IRAK4 and TRAF6 were genotyped in samples of sepsis-induced ALI (n = 272) and sepsis alone patients (n = 276), and tested for association in this case-control collection." (PMID 22901274, 2012). "Besides, USP13 inhibits the LPS-induced production of multiple inflammatory cytokines by deubiquitinating and inactivating IRAK4 and thus negatively regulates LPS-induced mouse sepsis shock." (PMID 41004574, 2025). "To test this hypothesis, we conducted a case-control study using tag SNP approach to investigate the association of variants in MyD88, IRAK1, IRAK4 and TRAF6 with susceptibility and outcome of sepsis-induced ALI in Chinese Han population." (PMID 22901274, 2012). "NFKBIA gene was iterated in 9 out of the 10 top pathways, MYD88 gene was enriched in 3 pathways, and IRAK4 was the only gene located on chromosome X. Their diagnostic accuracy was compared to IL6, which is used in our hospital protocol as a gold standard test for inflammatory reaction in sepsis." (PMID 34183713, 2021). "We next examined whether sepsis alters the expression of TLR9 and related response factors, such as myeloid differentiation primary response protein MYD88 and IL-1R-associated kinase–4 (IRAK4)." (PMID 26448624, 2015). "Interestingly, Toll‐like receptor signalling was detected in sepsis, specifically in the brain (prefrontal cortex and hippocampus), via the upregulation of genes such as CD14, TLR1, TLR2, TLR3, TLR7, IRAK3 and IRAK4." (PMID 37731199, 2023). "On the other hand, the myocardial expression of TLR9 itself and IRAK4, a factor downstream of TLR-MYD88, was not affected in the sepsis model we examined." (PMID 26448624, 2015).
Autoimmunity (7 papers, 2016 to 2024). The occurrence of an immune reaction against the organism's own cells or tissues. "Since expression in Sle1Tg7 is higher than the respective Sle1Tg7IRAKKD/KD mice, it confirms that the inflammatory environment of severe autoimmunity and signaling through IRAK4 contributes to the increase in TLR7 expression." (PMID 31354711, 2019). "In contrast, crossing ABIN1[D485N] mice to knock-in mice expressing catalytically inactive mutants of IRAK1 or IRAK4 prevented splenomegaly, autoimmunity, and liver and kidney inflammation." (PMID 27807192, 2016). "Our earlier studies had shown that autoimmunity and glomerulonephritis in ABIN1[D485N] mice were prevented by crossing to MyD88 KO mice or mice expressing kinase-inactive mutants of IRAK4 or IRAK1." (PMID 31694920, 2019).
leukemia (7 papers, 2022 to 2025). A malignant (clonal) hematologic disorder, involving hematopoietic stem cells and characterized by the presence of primitive or atypical myeloid or lymphoid cells in the bone marrow and the blood. "IRAK4 inhibitors have also entered human trials, with Emavusertib, a selective IRAK4 inhibitor, currently being evaluated in the Phase 1/2 TakeAim Leukemia trial (NCT04278768), which has shown promising preliminary efficacy." (PMID 40397075, 2025). "We showed that Celastrol and WA inhibit interleukin-1 receptor-associated kinase 4-mediated nuclear factor kappa-light-chain-enhancer of activated B cells signalling activation in splicing factor mutant MDS and leukaemia cells." (PMID 39988885, 2025). "The interleukin-1 (IL-1) signaling pathway, which is frequently hyperactivated in leukemia, potentiates UBE2O function via interleukin-1 receptor-associated kinase 4 (IRAK4)." (PMID 40426910, 2025). "The IRAK4 inhibitor emavusertib (CA-4948) has shown early safety and clinical activity in lymphoma and leukemia patients." (PMID 36675328, 2023). "Inhibition of IRAK4 to regulate UBE2O markedly increases the chromatin occupation of wild-type and inhibits the proliferation of MLL leukemia, which provides us a paradigm to develop a novel therapy method for aggressive MLL leukemia and other cancers caused by improper translocation." (PMID 37533513, 2022).
pneumococcal infection (7 papers, 2016 to 2022). Infections with bacteria of the species streptococcus pneumoniae. "One of the most important tests in the pediatric population is the interleukin-1 receptor-associated kinase 4 deficiency (IRAK-4), which predisposes children to severe and recurrent staphylococcal and pneumococcal infections." (PMID 35448079, 2022). "Mendelian disorders of immunity have previously been shown to result in phenotypes with unusual susceptibility to bacterial infection, such as pseudomonal and pneumococcal infections in patients with IRAK-4 deficiency." (PMID 27703454, 2016). "In particular, deficiencies in IL-1 signaling, including in IRAK4, Myd88 and NEMO, are associated with susceptibility to severe and recurrent pneumococcal infections during childhood." (PMID 30379943, 2018). "IRAK4 is the most extensively characterized TLR downstream signaling protein in invasive pneumococcal infection, and IRAK4 deficiency is associated with recurrent invasive pneumococcal infection in patients." (PMID 36543127, 2022).
primary immunodeficiency (7 papers, 2014 to 2025). "P. aeruginosa infection has been reported in children with primary immunodeficiency, including Wiskott–Aldrich syndrome, cyclic neutropenia, IRAK-4/MyD-88 deficiency, centromeric region instability, facial anomalies syndrome, and XLA." (PMID 33261572, 2020). "Two siblings were affected by IRAK-4 deficiency, a rare primary immunodeficiency with severe impairment of Toll-like receptor (TLR) and interleukin-1 receptor-mediated immunity." (PMID 24625087, 2014). "Genetic defects in bacterial sensing arising from mutations in canonical TLR signaling pathway genes such as IRAK4 and MYD88 are established causes of primary immunodeficiency." (PMID 37097753, 2023).
breast carcinoma (6 papers, 2013 to 2025). "Susan16 indicated that this missense mutation introduces a potential phosphorylation site in the extreme carboxy terminus (XCT) of the IRAK4 kinase domain, and that the XCT subdomain of IRAK4 performs biological functions in breast cancer." (PMID 35478439, 2022). "Studies have shown that the IRAK4 polymorphism rs4251545 is related to several diseases, such as severe sepsis, hepatocellular carcinoma (HCC), and breast cancer." (PMID 35478439, 2022). "However, in other cancer types (breast cancer and MDS), alternative splicing in PPP2R5A, MAP3K7, and IRAK4 has been linked to the activation of Akt and NF-κB pathway, TGF-β signaling, and inflammation pathway, respectively." (PMID 40694421, 2025). "Our results suggested that Chinese propolis and its major constituent – CAPE inhibited TLR4 signaling pathway molecules such as TLR4, MyD88, IRAK4, TRIF and NF- kB p65, which might be one of the major causes for Chinese propolis and CAPE to inhibit breast cancer cell proliferation and survive." (PMID 28950845, 2017).
inflammatory bowel disease (6 papers, 2009 to 2024). A spectrum of small and large bowel inflammatory diseases of unknown etiology. "In light of this, we developed a novel IRAK4 inhibitor and investigated its potential in the treatment of peritonitis and inflammatory bowel disease." (PMID 38675622, 2024).
pancreatic cancer (6 papers, 2019 to 2025). "CAFs also protect pancreatic cancer cells from gemcitabine-induced apoptosis through a NF-κB→IL-1β→IL-1R/associated kinase-4 (IRAK4) pathway; inhibition of IL-1β, or knockdown of IRAK4, dramatically augment gemcitabine chemosensitivity." (PMID 35267539, 2022). "Similarly, secreted IL-1β and the constitutively expressed IL-1 receptor associated kinase 4 (IRAK4) induce the activation of the NF-κB pathway both in CAFs and pancreatic cancer cells, alleviating the cytotoxicity of gemcitabine in pancreatic tumors." (PMID 33732706, 2021). "Inhibition of the downstream interleukin-1 receptor-associated kinase 4 (IRAK4) using two pharmacologic inhibitors, CA-4948 and PF06650833, resulted in reduced growth in pancreatic cancer cell lines and in xenograft models." (PMID 35606824, 2022). "In pancreatic cancers, CAFs expressing IRAK4 can induce resistance to chemotherapy by IL1β secretion that activate the NFκB pathway in pancreatic cancer cells." (PMID 35681591, 2022).
pneumococcal meningitis (6 papers, 2013 to 2025). An acute purulent infection of the meninges and subarachnoid space caused by Streptococcus pneumoniae, most prevalent in children and adults over the age of 60. "The patient with IRAK4 deficiency suffers from inguinal adenitis, pneumococcal meningitis, multiple hepatic abscesses, a soft tissue abscess in the thorax, the appearance of recurrent ringworm of the scalp, and cervical lymphadenopathy." (PMID 41209815, 2025). "Variations within the NOD2 (rs2067085) and IRAK4 (rs4251552) were associated with pneumococcal meningitis disease outcome." (PMID 27432718, 2016). "One toddler, in whom Staphylococcus aureus meningitis had developed at 7 months of age, died of pneumococcal meningitis at 13 months of age, and IRAK-4 mutation was subsequently diagnosed at postmortem examination." (PMID 23259937, 2013). "A significant part of IRAK4-deficient patients have lethal pneumococcal meningitis." (PMID 26825884, 2016). "Furthermore, pneumococcal meningitis patients with the IRAK4 risk allele had higher levels of IL-6 in their CSF with the diagnostic lumbar puncture, suggesting that these patients have an increased pro-inflammatory response during their disease." (PMID 27432718, 2016). "The strongest identified signal IRAK4 does imply a potential role of genetic variation in pneumococcal meningitis." (PMID 27432718, 2016).